ANO1 (anoctamin 1)
Diseases named in the same sentence as ANO1 in open-access papers (continued):
Sharing a sentence is not in itself a finding about the gene and the disease.
gastric cancer (27 papers, 2015 to 2025). A primary or metastatic malignant neoplasm involving the stomach. "Epithelial–mesenchymal transition (EMT), lymph node metastasis, and poor prognosis are clinicopathological characteristics associated with ANO1 overexpression in gastric cancer tissues." (PMID 40396170, 2025). "It has been reported that Ano1 is associated with poor prognosis in patients with gastric cancer and HNSCC." (PMID 29156699, 2017). "In gastric cancer patients, higher levels of ANO1 expression were linked to tumor spread." (PMID 35058979, 2022). "We previously found that Ano1, a calcium-activated chloride channel is overexpressed in gastric cancer and promotes gastric cancer cell invasiveness by regulating epithelial-to-mesenchymal transition." (PMID 28969029, 2017). "In gastric cancer, Ano1 promotes TGF-β secretion, and TGF-β signaling activation meditates Ano1-induced migration, invasion, and metastasis." (PMID 29156699, 2017). "Moreover, OIP5-AS1 accelerated cell growth via affecting miR-422a and ANO1 axis in gastric cancer cells." (PMID 35756672, 2022). "ANO1 translation is controlled by a number of microRNAs, including miR-9 in human bronchial epithelial cells, miR-9, miR-132 and miR-144 in colorectal cancer cells, and miR-381 in gastric cancer cells." (PMID 33250781, 2020). "Treatment of microRNA-381 inhibits metastasis of gastric carcinomas by suppressing ANO1." (PMID 29416639, 2018). "Another diagnostic marker for GISTs, DOG1 (Discovered on GIST 1, also known as Anoctamin-1), shows even higher sensitivity, detecting up to 36% of KIT-negative GISTs, but it is commonly expressed in gastric carcinomas and mesenchymal sarcomas such as leiomyoma and synovial sarcoma." (PMID 35804982, 2022). "It is also reported benzbromarone strongly inhibited ANO1 protein expression in gastric, oesophageal, and CRC cells and exerted antitumour effects in gastric cancer and GIST PDX models." (PMID 40396170, 2025). "In gastric cancer, KMT2A is recruited into the ANO1 promoter to induce H3K4 methylation of the ANO1 promoter to activate ANO1." (PMID 35058979, 2022). "In gastric cancer cells, the specificity protein 1 (SP1) was shown to bind ANO1 promoter and recruit the mixed lineage leukemia MLL1 protein to promoter region, facilitating histone H3K4 trimethylation, and subsequently promoting ANO1transcription." (PMID 33250781, 2020). "Acquiring an invasive phenotype is closely related with EMT and the involvement of ANO1 in EMT has been suggested by its modulation of the secretion of TGF-β and resultant repression of E-cadherin expression in gastric cancer cells." (PMID 29416639, 2018). "ANO1 expression was reported to be dependent on STAT6 in human bronchial epithelial cells, in esophageal keratinocytes and in gastric cancer cells." (PMID 33250781, 2020). "To analyze the expression level of ANO1 in PBMC from GIST patients, we established the range of expression levels of ANO1 in non-cancer healthy donors, gastric carcinoma patients and colorectal carcinoma patients." (PMID 27153560, 2016). "The highest expression levels of ANO1 transcripts relative to beta-actin were 3*10−5, 2.2*10−5 and 3*10−5 in 10 non-cancer healthy donors, 21 gastric carcinoma patients and 23 colorectal carcinoma patients, respectively." (PMID 27153560, 2016). "Inhibition of the STAT6/ANO1 pathway reduced proliferation, migration, and invasion by gastric cancer cells, suggesting that the STAT6/ANO1 pathway could represent a novel therapeutic target for gastric cancer." (PMID 40396170, 2025). "However, cell proliferation is not reduced in pancreatic ductal adenocarcinoma cells and gastric cancer cells treated with Ano1 shRNAs or inhibitors." (PMID 29156699, 2017).
colorectal cancer (26 papers, 2014 to 2025). A primary or metastatic malignant neoplasm that affects the colon or rectum. "Patients with colorectal cancer whose miR-132 expression is low and whose ANO1 expression is high have shorter progression-free survival." (PMID 40396170, 2025). "F. nucleatum has been implicated in the onset and advancement of colorectal cancer (CRC), with studies suggesting its involvement in modulating Anoctamin-1 (ANO1) expression." (PMID 39941737, 2025). "Collectively, these findings demonstrate that vitexicarpin not only suppresses colorectal cancer cell growth through ANO1 downregulation but also effectively overcomes gefitinib resistance in NSCLC cells." (PMID 40520165, 2025). "Recently, ANO1 has been identified as a promising therapeutic target for several malignancies, including colorectal cancer (CRC) and non-small cell lung cancer (NSCLC)." (PMID 40520165, 2025). "The largest range of copy number values was observed for ANO1, which ranged from the loss of both copies in the CCK81 cell line derived from a metastasis of colorectal cancer to an estimated 17 copies in the FADU hypopharyngeal carcinoma cell line." (PMID 36461044, 2022). "ANO1 is upregulated in a variety of cancers including glioma, colorectal cancer, and HNSCC, but its inhibition has led to decrease in tumor size, cell proliferation, and migration." (PMID 34281197, 2021). "Given that both Ani9 and vitexicarpin reduced ANO1 protein expression, we investigated whether these compounds inhibit colorectal cancer cell growth through ANO1 downregulation." (PMID 40520165, 2025). "Recent study revealed that TMEM16A (ANO1) was a direct target gene of miR-132, and was negatively regulated by miR-132 in colorectal cancer." (PMID 28193228, 2017). "TMEM16A (ANO1, DOG1 or TAOS2) has recently been identified as a calcium-activated chloride channel (CaCC) and is reported to be overexpressed in several malignancies; however, its expression and function in colorectal cancer (CRC) remains unclear." (PMID 25541940, 2014). "However, Ano1 depletion failed to affect tumor development in a model of colorectal cancer." (PMID 31383845, 2019).
leiomyosarcoma (21 papers, 2011 to 2026). An uncommon, aggressive malignant smooth muscle neoplasm, usually occurring in post-menopausal women. "Expression of Ano1 has been described in GIST, leiomyosarcoma, and squamous cell carcinoma of head and neck or the esophagus." (PMID 22912841, 2012). "Finally, we confirmed the expected overexpression of some genes: KIT and ANO1/DOG1 in GISTs, MDM2 and CDK4 in non-myxoid/round cells liposarcomas, CALD1 and tropomyosin genes (TPM1, TPM2) in leiomyosarcomas, PDGFB in DFSPs, MUC1/EMA in synovial sarcomas, and CD34 in SFTs." (PMID 23734203, 2013).
cyst (19 papers, 2015 to 2025). A sac-like closed membranous structure that may be empty or contain fluid or amorphous material. "Taken together, in mouse studies, ANO1 is a dominant driver of secretion-dependent cyst enlargement, while we also found that knockout of CFTR had no significant impact on cyst growth." (PMID 37686084, 2023). "ATP is released by cyst cells, accumulates in the cyst lumen and activates ANO1 via the stimulation of purinergic receptors." (PMID 37686084, 2023). "Transepithelial chloride secretion through cystic fibrosis transmembrane conductance regulator (CFTR) and TMEM16A (anoctamin 1) are known to drive cyst enlargement." (PMID 32859916, 2020). "The central aspects of ANO1 include its obvious pro-proliferative and de-differentiating properties, which after all may have a larger impact on cyst progression than fluid secretion." (PMID 37686084, 2023). "More studies are required to analyse the contribution of ANO1 to cyst formation in human tissue." (PMID 37686084, 2023). "Initial studies showed that Ca2+-activated ANO1 Cl− currents contribute to cyst growth." (PMID 37686084, 2023). "Similarly, the knockdown of ANO1 or ANO1 inhibitor suppresses cyst growth in the model of kidney cyst growth." (PMID 26811235, 2016). "Besides the cyst growth, ANO1 mediates acid secretion and protein reabsorption in the proximal tubules of the kidney." (PMID 26811235, 2016). "Recently, anoctamin 1 (ANO1, also known as TMEM16A) has been identified as a Ca2+-activated Cl- channel that promotes fluid secretion in PKD1 or PKD2 knockout models, and its pharmacological inhibition slows cyst growth in cell cultures, as well as in mice." (PMID 40722835, 2025). "It has been reported that exposure to scavengers of reactive oxygen species, such as glutathione, coenzyme Q10, or idebenone, blocks the growth of MDCK cysts by reducing the activation of TMEM16A (anoctamin 1), in which TMEM16A has been demonstrated to be essential for regulating cyst growth." (PMID 35050181, 2022). "Furthermore, the CFTR (cystic fibrosis transmembrane conductance regulator), the Ca2+-activated chloride channels TMEM16A (Anoctamin 1), but also the SLC member Slc12a2 have been identified as crucial aggravating co-factors for cyst enlargement in polycystic kidney disease." (PMID 35252349, 2022).
head and neck cancer (19 papers, 2013 to 2025). A primary or metastatic malignant neoplasm affecting the head and neck. "ANO1 encodes a calcium-dependent chloride channel protein and commonly amplifies to facilitate several cancers’ progression, including ovarian, prostate, breast, and head and neck cancers." (PMID 35237609, 2021). "An additional layer of complexity has recently been introduced by studies reporting channel-independent functions of ANO1, e.g. in regulating proliferation in head and neck cancer cells." (PMID 25823819, 2015). "For example, the anoctamin 1 (ANO1) gene encodes a calcium-activated chloride channel that is frequently amplified or upregulated in breast, prostate, and head-and-neck cancers." (PMID 24386311, 2013). "Additionally, the transmembrane protein TMEM16A gene (which encodes the Ca2+-dependent chloride channel ANO1) is downregulated, affecting the cell membrane potential and promoting the neoplastic process, for example, in HPV+ head and neck carcinoma." (PMID 37408210, 2023). "Co-inhibition of EGFR and ANO1 had an additive effect on head and neck cancer cell proliferation, suggesting that co-targeting of ANO1 and EGFR could enhance the clinical potential of EGFR-targeted therapy in HNSCC." (PMID 25823819, 2015). "Gene encoding anoctamin-1 (ANO1, aliases TMEM16A/DOG1), a calcium-dependent chloride channel protein, locates in 11q13, which is commonly amplified in several cancers, including the breast, the stomach, the ovary, and the prostate, glioblastoma, and head and neck cancer." (PMID 33803266, 2021). "Co-inhibition of EGFR and ANO1 had an additive effect on head and neck cancer cell proliferation, suggesting that co-targeting of ANO1 and EGFR could enhance the clinical potential of EGFR-targeted therapy in HNSCC and might delay or prevent resistance to single agent treatment." (PMID 25823819, 2015).
glioma (16 papers, 2016 to 2025). A benign or malignant brain and spinal cord tumor that arises from glial cells (astrocytes, oligodendrocytes, ependymal cells). "CaCCs such as TMEM16A (also known as ANO1) are overexpressed in various cancers, including lung, breast, colorectal, and gliomas." (PMID 40806720, 2025). "Anoctamin 1 (ANO1) was implicated in maintaining stemness and invasive potential in glioma cancer stem cells." (PMID 40497995, 2025). "More recently it has been shown that ANO1 directly interacts with and stabilises EGFRvIII in glioma cells." (PMID 36497413, 2022). "ANO1 is expressed in glioma cancer cell lines and patient glioma tissues, and expression correlates with a high pathological grade." (PMID 36497413, 2022). "NF-κB signaling has been shown to be activated in ANO1-overexpressing glioma, and the expressions of NF-κB-mediated genes are involved in proliferation, migration and invasion of glioma cells." (PMID 27212225, 2016). "Furthermore, several studies have shown that ANO1 knockdown reduces cell proliferation, migration, and invasion of glioma cells in vitro, suggesting a critical role in brain cancer cell function." (PMID 36497413, 2022). "Although the precise mechanisms of ANO1 in glioma progression remain unclear, it was first suggested that ANO1 expression is associated with activation of the nuclear factor-κB (NF-κB) signalling pathway." (PMID 36497413, 2022). "Overexpression of ANO1 in human astrocyte SVGp12 cells resulted in a decreased phosphorylation of NFκB inhibitor, IκB, accumulation of NFκB in the nucleus and activation of NFκB-dependent gene transcription; whereas knockdown of ANO1 in glioma U87MG cells inhibited NFκB activation." (PMID 33250781, 2020). "In addition, overexpression of ANO1 activates nuclear factor-κB (NF-κB) signaling, and knockdown of ANO1 suppresses the proliferation, migration, and invasion of glioma cells." (PMID 32357567, 2020). "In glial tumors, higher expression of ANO1 was correlated with higher histologic grade of tumors." (PMID 29416639, 2018). "In glioma, Ano1 overexpression activates the nuclear factor-κB signaling pathway." (PMID 29156699, 2017). "However, it has yet to be determined whether ANO1 also binds with NOTCH receptors in a similar manner to EGFR in glioma." (PMID 36497413, 2022). "ANO1 is also involved in cell migration and invasion by regulating the expression of MMP2 and MMP9 in glioma cells." (PMID 29416639, 2018). "However, it remains unclear whether ANO6 regulates glioma cell progression via ion current activity, scramblase activity, or a combination of these effects in synergy with other ANO proteins such as ANO1." (PMID 36497413, 2022).
oral squamous cell carcinoma (16 papers, 2010 to 2024). "In this study, we performed a cell-based screening to identify novel regulators leading to the downregulation of ANO1, and discovered cinobufagin, which downregulated ANO1 expression in oral squamous cell carcinoma CAL-27 cells." (PMID 34769467, 2021). "Anoctamin1 (ANO1), a calcium-activated chloride channel, is frequently overexpressed in several cancers, including oral squamous cell carcinoma (OSCC)." (PMID 34769467, 2021). "In particular, ANO1 is highly amplified and expressed in various carcinomas including oral squamous cell carcinoma (OSCC), prostate, breast, and esophageal cancers and is involved in the proliferation, metastasis, and invasion of cancer cells." (PMID 32899792, 2020). "Notably, Ani-D2 significantly reduced ANO1 protein expression levels and cell viability in an ANO1-dependent manner in PC-3 and oral squamous cell carcinoma CAL-27 cells." (PMID 32899792, 2020). "However, a detailed analysis of ANO1 expression in oral squamous cell carcinoma (OSCC) and its functions is missing." (PMID 24316695, 2014). "DOG1, TAOS2 and ORAOV2 are named so because ANO1 is strongly overexpressed in gastrointestinal stromal tumours (GIST) and oral squamous cell carcinomas." (PMID 26196390, 2015). "A similar correlation has been reported for cell lines from oral squamous cell carcinoma (TPCN2, CCND1, ORAOV1, ANO1, FADD, PPFIA1 and EMS1; FADD, PPFIA1 and EMS1)." (PMID 20664600, 2010). "We further analyzed expression of Ano1 in three different HNSCC cell lines: CAL-27 and CAL-33 (two tongue squamous cell carcinoma cell lines without genomic amplification of Ano1) and BHY cells (an oral squamous cell carcinoma cell line with known 11q13-amplification." (PMID 22912841, 2012).
glioblastoma (14 papers, 2012 to 2025). The most malignant astrocytic tumor (WHO grade IV). "Although ANO1 surface expression is important in the tumorigenesis of glioblastoma cells, the detailed molecular mechanisms underlying ANO1-surface expression remain to be fully understood." (PMID 32357567, 2020). "Next, to examine the functional expression of endogenous ANO1 channels and the association between ANO1 and 14-3-3γ in these glioblastoma cells, we constructed three different shRNAs against ANO1 and examined their silencing efficiency on ANO1 expression." (PMID 27212225, 2016). "Taking these findings together, we conclude that ANO1 is functionally expressed and associated with 14-3-3γ in glioblastoma cells such as U251, T98G and U138 cells." (PMID 27212225, 2016). "Finally, we examined whether the deficiency of CaMKIIβ or ANO1 also affects other glioblastoma cells." (PMID 32357567, 2020). "Under this pathological condition, activation of tyrosine kinases and G protein-coupled receptors increases intracellular Ca2+ concentration in glioblastoma cells, triggering the gating of ANO1." (PMID 36935741, 2023). "Suppression of ANO1 activity inhibits migration and invasion of these glioblastoma cell lines, indicating its therapeutic value." (PMID 36935741, 2023). "We thus conclude that CaMKIIβ plays a specific role in the surface expression of ANO1 and in the ANO1-mediated tumorigenic properties of glioblastoma cells, such as migration and invasion." (PMID 32357567, 2020). "In conclusion, the CaMKIIβ-mediated regulation of ANO1 surface expression plays a critical role in the oncogenic properties of glioblastoma cells." (PMID 32357567, 2020). "We tested the roles of CaMKIIβ and ANO1 in the tumorigenesis of U87 MG cells which is another glioblastoma cell showing high expression of ANO1." (PMID 32357567, 2020). "In this study, we found that Ca2+/Calmodulin-dependent protein kinase II (CaMKII) β specifically enhances the surface expression and channel activity of ANO1 in U251 glioblastoma cells." (PMID 32357567, 2020). "In the present study, we found that surface expression and channel activity of ANO1 are enhanced in a CaMKIIβ-specific manner in U251 and U87 MG glioblastoma cells." (PMID 32357567, 2020). "The present study uncovers the pivotal role of CaMKIIβ in the surface expression of ANO1 at the plasma membrane of glioblastoma cells." (PMID 32357567, 2020). "We previously reported that the surface expression and channel activity of ANO1 are critical for the tumorigenesis of glioblastoma cells." (PMID 32357567, 2020). "Cumulatively, these results strongly suggest that suppression of ANO1 surface expression by knockdown of CaMKIIβ is critical in the progression of human glioblastoma." (PMID 32357567, 2020). "Our results showed that CaMKIIβ and CaMKIIδ were expressed in U251 glioblastoma cells and only CaMKIIβ-overexpression enhanced the ANO1-mediated current in the cells." (PMID 32357567, 2020). "The specific regulatory mechanism of ANO1 by CaMKIIβ should prove to be helpful in understanding the functional roles of ANO1 in glioblastoma cells." (PMID 32357567, 2020). "We also found that suppression of CaMKIIβ using small interfering RNA (siRNA) or a CaMKII inhibitor, KN-93, reduced the surface expression and channel activity of ANO1 in glioblastoma cells." (PMID 32357567, 2020). "Recently, we also reported that ANO1 (Anoctamin1 or TMEM16A) is involved in tumorigenesis of glioblastoma cells." (PMID 32357567, 2020). "ANO1, a Ca2+-activated chloride channel, is highly expressed in glioblastoma cells and its surface expression is involved in their migration and invasion." (PMID 32357567, 2020). "The mRNA and protein levels of endogenous ANO1 in U251 glioblastoma cells were clearly reduced by approximately 70% following treatment with ANO1 shRNA." (PMID 32357567, 2020).